IRF8 (interferon regulatory factor 8)
Diseases named in the same sentence as IRF8 in open-access papers (continued):
Sharing a sentence is not in itself a finding about the gene and the disease.
Immunodeficiency (14 papers, 2012 to 2024). Failure of the immune system to protect the body adequately from infection, due to the absence or insufficiency of some component process or substance. "IRF8 deficiency in humans was previously documented and the subjects suffered from severe immunodeficiency due to depletion or impaired functions of dendritic cell subsets, monocytes, and NK cells." (PMID 38296975, 2024). "It is also reported that mutation in human IRF8 has an influence on primarily myeloid cells, and causes immunodeficiency." (PMID 38965205, 2024). "IRF8 is expressed in macrophages and dendritic cells and mutations of the human IRF8 gene results in two different immunodeficiencies." (PMID 36756122, 2023). "IRF-8(-) mice are not only associated with immunodeficiency due to the defects in functions of macrophages, but also can progress to CML-like diseases." (PMID 35211408, 2022). "IRF8 deficiency results in a severe immunodeficiency humans as characterized by susceptibility to infections due to loss of DC subsets, CD14+ and CD16+ monocytes and a decreased level of NK cells with reduced activity." (PMID 36078039, 2022). "A mono-allelic T80A mutation of IRF8 was associated with a milder AD immunodeficiency and a partial reduction of CD11c+/CD1c+ circulating DCs, which led to BCGosis without other infectious diseases." (PMID 36569938, 2022). "IRF8 provides more evidence that the IFN pathway is important in the balance between SLE risk and infection as mutations that impair IRF8 transcriptional activity have been found to cause immunodeficiency." (PMID 36327221, 2022). "Deficiency of IRF8 in mice causes myeloproliferative disease and immunodeficiency and affected animals are more susceptible to viral and bacterial infection." (PMID 23166780, 2012). "The role of IRF8 in DC development is conserved in humans as point mutations (T80A, K108E) in the IRF8 DNA-binding domain are found in individuals with immunodeficiency accompanied by impaired DC subset production." (PMID 23251709, 2012). "Thus, it was suggested that growing up with immunodeficiency due to loss of IRF8 might interfere with the normal development of functions exerted by the lumbar CPG network because IRF8 plays a role in the normal development of the lumbar CPG network." (PMID 38239832, 2023). "A recent study has addressed some of these points and has looked into IRF8 immunodeficiencies and into in vitro development of DCs from progenitors." (PMID 33101275, 2020). "IRF8(-) mice are accompanied with immunodeficiency, and are also sensitive to various pathogens." (PMID 35211408, 2022). "An autosomal recessive IRF8 deficiency, K108E, was associated with a complete lack of dendritic cells and resulted in a severe immunodeficiency." (PMID 36078039, 2022). "However, more widespread immune dysfunction is predicted from the multiple roles ascribed to IRF8 in immune cell development and function." (PMID 29128673, 2018). "However, whether this immune deficiency arising from the absence of IRF8 influences the development of the neuronal network in the spinal cord is unknown." (PMID 38239832, 2023). "The central role of IRF8 in host defence and myeloid cell development is not restricted to mice and an inactivating mutation in the IRF8 gene in humans is associated with an autosomal recessive severe immunodeficiency with a complete lack of circulating monocytes and dendritic cells." (PMID 23166780, 2012).
colon carcinoma (13 papers, 2011 to 2024). "The correlation between decreased IRF8 and increased OPN expression in colon carcinoma underlines the significance of IRF8 in immune checkpoint mechanisms within GI cancers." (PMID 38646539, 2024). "The MDSC-IL-10-STAT3-DNMT3b-IRF8 pathway is also involved in the molecular progression from inflammation to colon cancer initiation." (PMID 36966276, 2023). "In human colon cancer cells, IRF8 protein levels are inversely correlated with the metastatic phenotype." (PMID 36078039, 2022). "It has been suggested that colon cancer cells silence IRF8 expression through inhibition of pSTAT1 function at the IRF8 promoter." (PMID 36078039, 2022). "IFNγ-induced IRF8 acts in concert with NF-κB to regulate iNOS expression in both colon carcinoma and myeloid cells." (PMID 26497740, 2015). "These authors also examined the expression of IRF8 by RT-PCR and observed ectopic IRF8 expression in nasopharyngeal, esophageal and colon cancer cell lines." (PMID 25120651, 2014). "In colon carcinoma cells, IRF8 induced by IFNγ sensitizes them to Fas-mediated apoptosis, but the silencing of the IRF8 gene by methylation of its promoter region renders them resistance to IFNγ-mediated apoptosis." (PMID 21261980, 2011). "Interferon regulatory factor 8 (IRF8) transcriptionally suppress secreted OPN expression in CD11b+Ly6ClowLy6G+ myeloid cells, which caused decreased interaction between OPN and CD44 receptor in T cell and suppresses immune escape in colon cancer." (PMID 36906534, 2023). "IRF8 functions as an apoptosis regulator in several types of human tumor cells and mice with IRF8 deletion only in the colon epithelial cells develop significantly more colon tumors than the littermate control mice." (PMID 36078039, 2022). "Promoter hypermethylation and gene silencing of IRF8 abrogates cellular response to interferon stimulation and overexpression of IRF8 in nasopharyngeal, esophageal and colon cancer cell lines could inhibit clonogenicity." (PMID 31684858, 2019). "Because pSTAT1 enhances iNOS expression through the intermediate factor IRF8 in human colon carcinoma cells, we hypothesized that IFNγ activates IRF8 to regulate iNOS expression in myeloid cells as well." (PMID 26497740, 2015). "Moreover, IRF8 is a metastasis suppressor in solid tumors and metastatic tumor cells use DNA hypermethylation to repress IRF8 expression to evade apoptotic cell death and to acquire a metastatic phenotype in human colon carcinoma." (PMID 24709797, 2013). "The dysregulation, characterized by decreased IRF8 and increased OPN expression in colon carcinoma cases, exemplifies the orchestrated orchestration of these molecules in shaping tumor immune tolerance and evasion." (PMID 38646539, 2024). "IRF1 and IRF8 are member of the IFN regulatory factor family; both of them were proven to be suppressor of colon cancer." (PMID 32812032, 2020).
multiple sclerosis (12 papers, 2011 to 2024). A progressive autoimmune disorder affecting the central nervous system resulting in demyelination. "Sequence variants near the IRF8 gene have been implicated as key risk factors for inflammatory bowel disease and multiple sclerosis." (PMID 38716195, 2024). "Recent genome‐wide SNP analysis has identified IRF8 as a susceptibility factor for multiple sclerosis." (PMID 29973381, 2018). "Variants in TNFRSF1A and in the vicinity of IRF8 were confirmed to be associated in these independent cohorts, which supports the role of these loci in etiology of multiple sclerosis." (PMID 21552549, 2011). "rs2280381 is found 64 kb downstream of IRF8, and is in LD with the coding region, but independent from a susceptibility allele for multiple sclerosis (rs17445836), 1 kb away." (PMID 22046141, 2011). "Irf8 is a critical TF for microglial activation and promotes neuroinflammation under neurodegenerative conditions of AD and EAE, a mouse model for multiple sclerosis." (PMID 31959236, 2020).
myeloid leukemia (12 papers, 2008 to 2023). A clonal proliferation of myeloid cells and their precursors in the bone marrow, peripheral blood, and spleen. "Intriguingly, in the “Human Phenotype” gene ontology category, acute monocytic and myeloid leukemia are top terms associated with the IRF8-targeted loci." (PMID 33673123, 2021). "Here, we define another mechanism for decreased RASSF5 transcription; decreased Irf8 expression as found in myeloid leukemias or with aging." (PMID 37247756, 2023). "To identify target genes that mediate effects of Irf8 (referred to as Icsbp in prior studies), we hybridized chromatin that coimmunoprecipitated from U937 myeloid leukemia cells with Irf8 to a CpG island microarray." (PMID 37247756, 2023). "We determined that transcription of the PTPN13 promoter (encoding Fap1) was repressed by Icsbp/Irf8 (interferon consensus sequence binding protein/interferon regulatory factor 8) in myeloid leukemia cells." (PMID 29899829, 2018). "IRF8 was originally characterized as a tumor suppressor gene in certain myeloid leukemias, notably CML." (PMID 26008967, 2015). "Specifically, in humans, IRF8 expression was high in normal hematopoietic cells but impaired in myeloid leukemia." (PMID 23658517, 2013). "Thus, acting as a tumor suppressor by promoting cell differentiation, IRF8 expression is frequently lost in myeloid leukemias." (PMID 37760612, 2023). "In addition to the role of IRF8 in myeloid leukemia, recently its role in suppressing acute lymphoblastic leukemia has been described." (PMID 29593731, 2018). "In adult myeloid leukemias we found significant associations between the variant allele of PML_rs9479 and decreased AML risk (OR = 0.61 (0.38-0.97), and between variant alleles of IRF8_ rs10514611 and ARHGAP26_rs187729 and increased CML risk (OR = 2.4 (1.12-5.15) and 1.63 (1.07-2.47), respectively)." (PMID 24886876, 2014). "Based on observations in myeloid leukemia, IRF-8 may regulate Fas responsiveness by acting as a transcriptional activator of pro-apoptotic genes, such as caspases, and/or a transcriptional repressor of anti-apoptotic genes, such as PTPN13 (FAP-1) or members of the Bcl-2 family." (PMID 23028998, 2012). "IRF8 has been characterized as a major transcription factor in the IRF family of proteins, and its levels are dramatically decreased in CML and myeloid leukemia cells." (PMID 23658517, 2013). "Without IRF8, hematopoietic cells in human myeloid leukemia patients rapidly proliferate and remain undifferentiated." (PMID 37760612, 2023). "A tumor suppressor role has been described for IRF8, as very low or absent IRF8 mRNA was found in the peripheral blood of the majority of human myeloid leukemias." (PMID 29593731, 2018).
acute myeloid leukemia (11 papers, 2013 to 2026). Acute myeloid leukemia (AML) is a group of neoplasms arising from precursor cells committed to the myeloid cell-line differentiation. "However, IRF8 has recently been reported to function as an acute myeloid leukemia (AML)-specific susceptibility factor and promote AML cell proliferation." (PMID 36078039, 2022). "Although traditionally considered a tumor suppressor, recent studies suggest a pro-oncogenic role for IRF8, particularly in acute myeloid leukemia (AML), where elevated IRF8 expression correlates with poor prognosis." (PMID 41596598, 2026). "The retinoic acid receptor-α agonist SY-1425 can promote the differentiation of acute myeloid leukemia cells with high expression of RARA or IRF8 genes, thereby inhibiting tumor growth." (PMID 40672386, 2025). "We and others have identified aberrant expression of IRF8 transcripts, including novel splice variants, in acute myeloid leukemia (AML), but studies have not investigated the prognostic significance of these transcripts." (PMID 23967110, 2013). "In CML, expression of Irf8 increases with remission, decreases with relapse, and is lowest during progression to myeloid blast crisis (BC or acute myeloid leukemia [AML])." (PMID 37247756, 2023). "In humans, substantially reduced IRF8 mRNA levels have been reported in patients with CML or acute myeloid leukemia (AML)." (PMID 26008967, 2015). "Additionally, Syros Pharmaceuticals has utilized its gene control platform to identify acute myeloid leukemia patients and subgroups of myelodysplastic syndrome with SEs of RARA or IRF8 genes and discovered biomarkers that can recognize these SEs." (PMID 40672386, 2025). "Indeed, IRF8 has been shown to function as a suppressor of acute myeloid leukemia (AML)." (PMID 36078039, 2022). "Its tumor suppressor activity is supported by mice with a null mutation of IRF8 developing a CML-like syndrome and lack of IRF8 expression in patients with chronic and acute myeloid leukemia." (PMID 24886876, 2014). "Notably, IRF8 expression was found dramatically decreased in patients with CML and acute myeloid leukemia (AML)." (PMID 23658517, 2013).
colitis (11 papers, 2017 to 2024). Inflammation of the colon. "In mice, IRF8 deficiency promotes colitis mediated by Th17 and Tfh cells and impairs gastric innate immunity against infection." (PMID 37645044, 2023). "IRF8 deficiency in IECs is linked to colitis-related colon tumorigenesis in both humans and mice." (PMID 37645044, 2023). "Research showed that IRF8-regulated Tfh could function as B-cell-independent, pathogenic, mediators of colitis." (PMID 37063924, 2023). "Targeted deletion of irf8 in T cells (CD4-IRF8KO) has been shown to exacerbate colitis and experimental autoimmune uveitis (EAU), a mouse model of human uveitis." (PMID 33803441, 2021). "IRF8 was shown to interact with RORγt to restrain Th17 cell differentiation and colitis in mice." (PMID 38039135, 2023). "Interferon regulatory factor 8- (IRF8-) regulated Tfhs can function as pathogenic mediators of colitis in IBD, which is independent of B cells." (PMID 31687412, 2019). "Tfh frequencies have been shown to be elevated in the germinal centers of MLNs in murine colitis models and disruption of Tfh differentiation by IRF-8 (interferon regulatory factor-8) downregulation can exacerbate the disease." (PMID 35163775, 2022). "However, a previous study using experimental colitis showed a negative correlation between IRF8 and Th17." (PMID 35664436, 2022).
lung carcinoma (9 papers, 2014 to 2026). "IRF8 has been reported to suppress ATK and induce P27 expression to cause lung cancer cell senescence, and IRF8 methylation leads to NSCLC recurrence." (PMID 39384770, 2024). "In breast and lung cancer, IRF8 is downregulated as a result of promoter hypermethylation, and a higher IRF8 expression level was associated with a better prognosis." (PMID 36078039, 2022). "Previously, in the context of lung cancer susceptibility, Long and colleagues observed a cis-regulatory element shared across many lung cell types overlapping rs3769823 and noted that this variant is predicted to alter IRF8 DNA binding." (PMID 41542517, 2026). "Except for certain tumor-infiltrating immune cells, including certain B cells, pDC and myeloid cells, IRF8 is down-regulated in most cell types and is undetectable in human lung cancer cells." (PMID 36078039, 2022). "Specifically, the cooperativity of IRF8 was highly perturbed in lung cancer, which was further validated by two independent lung squamous cell carcinoma (LUSC) and lung adenocarcinoma (LUAD) datasets." (PMID 27496222, 2016). "In the present study, we examined IRF8 methylation and mRNA expression in lung cancer cell lines, and IRF8 methylation and protein expression in primary NSCLCs, and compared the results with the clinicopathological features." (PMID 25120651, 2014). "Aberrant methylation of IRF8 has been reported in multiple carcinoma cell lines, including four lung cancer cell lines (A549, H292, H358 and H1975) by methylation-specific PCR assay." (PMID 25120651, 2014). "The changes in IRF8 mRNA expression, prior to and following treatment with a demethylating agent and methylation itself, were examined in 13 lung cancer cell lines by quantitative polymerase chain reaction (qPCR) and pyrosequencing." (PMID 25120651, 2014). "The IRF8 methylation level was strongly correlated with the change in mRNA expression in lung cancer cell lines and with the protein expression level in primary tumors." (PMID 25120651, 2014). "Identifying new master transcriptional regulators of myeloid cell differentiation and investigating the role of known interferon regulatory factor 8 (IRF8), transcriptional factor for DC differentiation, can help control systemic tumor‐induced immunosuppression in lung cancer." (PMID 39083441, 2025). "The detailed functions of IRF2, IRF4, and IRF8 in lung cancer are complex and controversial." (PMID 39384770, 2024). "IRF8 is also a tumor suppressor, and it has the ability to induce senescence in lung cancer cells." (PMID 37507593, 2023). "A study has shown that IRF8 inhibits the tumor by inducing the senescence of lung cancer cells." (PMID 35675043, 2022). "In lung cancer cells, IRF8 negatively regulates Akt phosphorylation, inducing cellular senescence." (PMID 33766090, 2021). "In addition, inhibition of IRF8 expression levels has been found to increase tumor growth in lung cancer xenografts, indicating a role for IRF8 in progression of late-stage lung cancers." (PMID 33766090, 2021). "Finally, the disrupted cooperation of IRF8 in lung cancer was validated by two independent lung squamous cell carcinoma (LUSC) and lung adenocarcinoma (LUAD) datasets, and its contribution to tumor progression and patient survival was further investigated." (PMID 27496222, 2016). "Further studies are required to understand the function of IRF8 in lung cancer pathogenesis." (PMID 25120651, 2014). "Considering the previous methylation studies of IRF8 in cancer sites, including lung cancer cell lines, we hypothesized that IRF8 may also be frequently methylated in NSCLC." (PMID 25120651, 2014). "In the present study, it was demonstrated that the re-expression of IRF8 mRNA occurs in lung cancer cell lines following treatment with a demethylating agent, and that it is correlated with the methylation status of the gene, although the level of re-expression was varied." (PMID 25120651, 2014).
lung carcinoma (continued). "Similarly, IRF8-induced expression of p27 induced lung cancer cell senescence." (PMID 36078039, 2022).
Autoimmunity (8 papers, 2015 to 2025). The occurrence of an immune reaction against the organism's own cells or tissues. "Together these studies strongly suggest that genetic variations of IRF8 in B cells can modulate susceptibility to autoimmunity including SSc." (PMID 38296975, 2024). "Considering that cGas-Sting axis mediates autoimmune phenotypes in Trex1−/− mice, we investigated the roles of Irf8 in autoimmunity in Trex1-deficient mice." (PMID 35973990, 2022). "We have also shed light on the mechanisms by which USP7 controls IRF4 and IRF8 expression in cDCs in the context of autoimmunity." (PMID 40247205, 2025). "Our observations further highlight the fundamental role of Ezh2 in regulating IRF4 and IRF8 in tolerogenic DCs and limiting autoimmunity." (PMID 32899608, 2020). "Here authors show that IRF8 is also involved in cytosolic DNA sensing via its phosphorylation-dependent association to the adaptor protein STING, thus representing an important checkpoint between immune response and autoimmunity in monocytes." (PMID 35973990, 2022). "However, the correlation between IRF8 expression and autoimmunity remains controversial, and the available findings are contradictory." (PMID 35388006, 2022). "Eradicated circulating DCs by degrating IRF-8 and induced autoimmunity by producing IFNα." (PMID 35464474, 2022). "IRF-8 would then serve to modulate expression of the ACHR in thymus and thereby influence the balance supporting autoimmunity and tolerance." (PMID 30308012, 2018).